TTR (transthyretin)
Diseases named in the same sentence as TTR in open-access papers (continued):
Sharing a sentence is not in itself a finding about the gene and the disease.
amyloidosis (continued). "In this article, the latest advancements (from 2020 onward) in the treatment of amyloidosis associated with the misfolding and fibrillization of the transthyretin (TTR) protein will be reviewed." (PMID 39337457, 2024). "The transthyretin TTR c.325G>C (p.Glu109Gln, also known as p.Glu89Gln) mutation, which causes a hereditary type of amyloidosis, is common in many Mediterranean countries." (PMID 39273284, 2024). "Hereditary transthyretin (TTR) amyloidosis (ATTRv) is an inherited peripheral neurodegenerative disease caused by mutations in the TTR gene." (PMID 38486098, 2024). "Conversely, secondary forms, such as amyloidosis linked to mutations in the transthyretin (TTR) gene or syndromic disorders like Alström syndrome or Myhre syndrome, are better characterized." (PMID 38666937, 2024). "Familial amyloidosis polyneuropathy associated with variants of TTR (FAP-TTR) is an infrequent, multisystemic disease, with predominant involvement of the peripheral nervous system." (PMID 38537102, 2024). "We found no other TTR variants in AA patients with either heart failure or arrhythmia who also had multiple other diagnoses associated with TTR amyloidosis." (PMID 38541013, 2024). "Hereditary transthyretin (ATTRv, v for variant) amyloidosis with polyneuropathy is a rare disease caused by mutations in the transthyretin gene." (PMID 38622453, 2024). "Transthyretin (TTR) is a plasma protein implicated in three amyloid diseases: familial amyloidotic polyneuropathy, familial amyloid cardiomyopathy, and senile systemic amyloidosis." (PMID 39065728, 2024). "The mechanisms underlying TTR misfolding in ATTRwt amyloidosis are not fully understood, although deficits in proteostasis, proteolysis-induced fragmentation of TTR, environmental factors, and aging seem to play a key role." (PMID 37566193, 2024). "Coding mutations in the TTR gene cause TTR misfolding and are responsible for a hereditary form of amyloidosis, TTR-related amyloidosis (hATTR)." (PMID 38523305, 2024). "Hereditary transthyretin (ATTRv) amyloidosis is caused by pathogenic gene variants in the gene encoding transthyretin (TTR)." (PMID 38337504, 2024). "For this study, we described the main demographic and clinical characteristics of 3167 study participants who were at risk of hATTR amyloidosis, as part of the TRAMmoniTTR study, which included TTR genetic testing of this at-risk population." (PMID 39458146, 2024). "Over 130 variants in the TTR gene have been identified to cause pathogenic ATTRv amyloidosis, with very few (V30M, V122I [c.424G>A; p.V142I]) being sufficiently described in the literature." (PMID 38241252, 2024). "This is often the case in older men with an African descent where gammopathies are more common and 4% of the population carry the V122I TTR variant which also predisposes to amyloidosis." (PMID 38275011, 2024). "Despite the close contact of microvasculatures with circulating TTR, the effects of variant TTR on endothelial cells received little attention except the disrupted blood–nerve barrier or vascular compression by amyloid deposits." (PMID 37902278, 2024). "In patients with amyloidosis who have both monoclonal gammopathy and a TTR variant, it is imperative to discern the tissue type of the amyloid to deduce the correct diagnosis." (PMID 39736876, 2024). "Individuals who carry a pathogenic TTR gene variant (TTRv) are at high risk of developing ATTRv amyloidosis, prompting clinicians to perform regular screening for disease onset in this population." (PMID 38337504, 2024). "Coding mutations in the Transthyretin (TTR) gene cause a hereditary form of amyloidosis characterized by a complex genotype-phenotype correlation with limited information regarding differences among worldwide populations." (PMID 38523305, 2024). "The prevalence of the TTR P/LP variants was higher in our study (3%), most likely due to the current inclusion criteria (one criterion was being diagnosed with hATTR amyloidosis—see Section 2)." (PMID 39458146, 2024).
amyloidosis (continued). "TTR amyloidosis includes hereditary forms, caused by mutations in the TTR gene, and wild-type forms based on the absence of TTR mutations." (PMID 38256243, 2024). "Mutations of TTR can be associated with accumulation of insoluble transthyretin deposits in various organs and tissue causing hereditary or variant TTR amyloidosis (ATTRv)." (PMID 38410247, 2024). "Hereditary transthyretin (ATTRv) amyloidosis is an autosomal dominantly inherited systemic disorder arising from mutations within the transthyretin (TTR) gene." (PMID 39010205, 2024). "TTR amyloidosis can be hereditary, caused by mutations in the TTR gene, or acquired in older individuals." (PMID 39598489, 2024). "Amyloidosis experts have proposed optimal management strategies for asymptomatic TTR gene mutation carriers; however, clinical practice for carrier management often differs between countries or regions because of differences in medical settings." (PMID 37828588, 2023). "We identified two patients with transthyretin (ATTR) amyloid myopathy (one ATTR variant amyloidosis, ATTRv; one wild-type ATTR amyloidosis, ATTRwt)." (PMID 35581484, 2023). "Hereditary transthyretin (ATTRv; "v" for variant) amyloidosis is a rare systemic disease caused by mutations in the transthyretin (TTR) gene." (PMID 36064814, 2023). "In this article, after summarizing the general overview of ATTRv amyloidosis, we discuss the follow-up strategy for TTR gene mutation carriers and diversity of methods used to capture the signs of disease onset." (PMID 37828588, 2023). "Patients with a definitive diagnosis of ATTR-CM should undergo genetic testing (search for TTR gene mutations) to distinguish ATTRv amyloidosis from ATTRwt." (PMID 37901600, 2023). "Amyloidosis due to the transthyretin Ser77Tyr mutation (ATTRS77Y) is a rare autosomal‐dominant disorder, characterized by carpal‐tunnel syndrome, poly‐ and autonomic‐neuropathy, and cardiomyopathy." (PMID 36772971, 2023). "More than 120 transthyretin mutations related to amyloidosis have been found documented, with some genetic variations confined to geographical areas or ethnic groupings." (PMID 37720240, 2023). "As TTR gene mutation carriers are at risk of developing ATTRv amyloidosis, monitoring of early signs and symptoms of disease onset in this population is crucial." (PMID 37828588, 2023). "The phenotypic presentation of ATTRv amyloidosis is clinically heterogeneous and can be predominantly neurologic, predominantly cardiac, or mixed phenotype, depending on the particular TTR variant and other factors." (PMID 37946256, 2023). "Hereditary transthyretin (ATTRv) amyloidosis is an autosomal dominant disorder associated with mutations in the transthyretin (TTR) gene." (PMID 37828588, 2023). "Conversely, heart involvement is the leading cause of morbidity and mortality in AL and TTR amyloidoses." (PMID 37115472, 2023). "Peripheral neuropathy caused by amyloidosis is one of the well-recognised sequelae of mutations in the transthyretin gene (TTR)." (PMID 37381065, 2023). "Currently, a total of 42 protein precursors linked to amyloidosis have been pinpointed, with Transthyretin (ATTR) standing out among them." (PMID 37653545, 2023). "Hereditary transthyretin (ATTRv) amyloidosis is a rare and autosomal dominant disorder associated with mutations in the transthyretin gene." (PMID 37828588, 2023). "These early studies preceded recognition of the pathogenesis of clinical subtypes of amyloidosis and the establishment of transthyretin deposition as the cause of what was then referred to as “senile” amyloidosis." (PMID 37335725, 2023). "Familial transthyretin amyloidosis is a rare genetic disease of the Transthyretin (TTR) gene that causes the protein to misfold." (PMID 37177842, 2023). "Hereditary (mATTR; familial) amyloidosis is caused by the deposition of misfolded mutated transthyretin protein, a transport protein normally produced by the liver and commonly found in the serum." (PMID 36968873, 2023).
amyloidosis (continued). "Variant transthyretin amyloidosis (A-ATTRv) is an autosomal dominant disease caused by a range of TTR gene variants which entail great phenotypical heterogeneity and penetrance." (PMID 37653545, 2023). "The involvement of clinically or pathologically variable disease manifestations is also characteristic for a hereditary form of amyloidosis caused by transthyretin amyloid protein (ATTR)." (PMID 37993462, 2023). "A liver-produced protein called altered transthyretin (ATTRm) is the most frequently identified cause of amyloidosis." (PMID 36982754, 2023). "hATTR amyloidosis is caused by the deposition of misfolded precursor protein TTR as insoluble amyloid fibrils in multiple organs, ultimately disrupting normal tissue structure and function." (PMID 36829087, 2023). "Transthyretin-mediated (ATTR) amyloidosis is caused by misfolding of the precursor protein transthyretin (TTR)." (PMID 37740174, 2023). "Transthyretin amyloidosis (ATTR amyloidosis) is a progressive, multisystemic, life-threatening disease resulting from the deposition of variant or wild-type (ATTRwt amyloidosis) transthyretin amyloid fibrils in various tissues and organs." (PMID 37946256, 2023). "Patisiran, is cleared for the treatment of rare polyneuropathies caused by hereditary transthyretin-mediated amyloidosis and works by binding and degrading transcripts of transthyretin messenger RNAs." (PMID 37058073, 2023). "It is used to treat polyneuropathy in adults, which is caused by inherited TTR-mediated amyloidosis." (PMID 37238946, 2023). "Over 140 different TTR gene mutations have been identified, but only some are associated with most ATTRv amyloidosis cases." (PMID 37901600, 2023). "This decrease in protein levels reduces the amyloid accumulation associated with transthyretin-mediated amyloidosis, ultimately slowing the progression of the disease." (PMID 37895887, 2023). "Amyloidosis specialists worldwide have actively developed expert recommendations to manage TTR gene mutation carriers and improve the early diagnosis of ATTRv amyloidosis." (PMID 37828588, 2023). "Amyloidosis is caused by the deposition of the misfolded transthyretin protein (TTR), the molecule that is produced by hepatocytes and is responsible for transferring vitamin A and thyroxine." (PMID 36986436, 2023). "Mutations in the TTR gene cause the liver to produce abnormal TTR protein, which accumulates as deposits in body tissues (amyloidosis) which can cause tissue damage." (PMID 37381065, 2023). "Amyloidosis experts worldwide have issued several recommendations for the management of asymptomatic TTR gene mutation carriers, as well as those for continuous monitoring of disease progression after disease onset." (PMID 37828588, 2023). "Family members of patients with ATTRv amyloidosis often have pathogenic mutations in the TTR gene and are at risk of developing the disease; thus, they are primary targets for monitoring early signs and symptoms." (PMID 37828588, 2023). "Theseresults suggest that interactions of TTR with red blood cells, whosemembranes are rich with these lipids, can trigger irreversible aggregationof TTR and cause transthyretin amyloidosis." (PMID 38033106, 2023). "Consequentially, TTR fibrils are predisposed to misfolding, abnormal aggregation, and subsequent extracellular deposition, as happens in other systemic amyloidoses." (PMID 37869146, 2023). "Another significant association was observed between a known LOF variant in TTR, p.Val142Ile (rs76992529), and amyloidosis (phecode = 270.33, OR = 29.9, P = 9.07 × 10–15)." (PMID 38037155, 2023). "Amyloidosis associated with TTR is known as TTR amyloidosis or ATTR (Amyloid Transthyretin) amyloidosis." (PMID 37764220, 2023). "For the appropriate pre- and post-symptom onset testing for ATTRv amyloidosis, it is important to capture the signs of disease onset in asymptomatic TTR gene mutation carriers and monitor disease progression after diagnosis." (PMID 37828588, 2023).
amyloidosis (continued). "SSA is caused by the aggregation of wild-type protein (WT-TTR), mainly in the heart, and more than 100 various point mutations are related with the other three TTR-related amyloidosis." (PMID 36009368, 2022). "This is particularly true for amyloid diseases caused by normal circulating levels of wild type proteins such as TTR." (PMID 35237660, 2022). "Hereditary transthyretin (ATTRv) amyloidosis is a rare disease caused by transthyretin gene (TTR) mutation." (PMID 36186469, 2022). "Hereditary amyloidogenic transthyretin (ATTRv; v for “variant”) amyloidosis is caused by mutations in the transthyretin (TTR) gene and is an autosomal dominantly inherited, debilitating, progressive and, if left untreated, fatal multisystem disorder." (PMID 33188616, 2022). "Here, we report on a novel TTR mutation underlying late-onset ATTRv amyloidosis with mixed neuropathic and cardiac phenotype initially misdiagnosed as ATTRwt amyloidosis." (PMID 36494773, 2022). "More than 10 years after the discovery that the V30M variant TTR was the causative protein of familial amyloid polyneuropathy, the first mouse model of TTR amyloidosis was published by the Araki’s group." (PMID 35237660, 2022). "The pathogenetic model of ATTRv amyloidosis indicates that amyloidogenic, usually missense, mutations destabilize the native TTR favouring the dissociation of the tetramer into partially unfolded species that self-assemble into amyloid fibrils." (PMID 33188616, 2022). "The second most recognized subtype is transthyretin amyloid protein (ATTR) amyloidosis, comprising both the variant ATTR (ATTRv) and wild-type ATTR (ATTRwt)." (PMID 36471404, 2022). "Increasing transthyretin in tissues is the main reason for this disease and is caused by hereditary transthyretin-mediated amyloidosis." (PMID 35326259, 2022). "The most common amyloidosis subtypes, immunoglobulin light chain (AL), serum amyloid A (AA), and transthyretin (ATTR), are associated with systemic disease." (PMID 35810311, 2022). "Under proper conditions, wild-type TTR (wt-TTR) or TTR variants polymerize into amyloid fibrils in vivo, similarly to over 30 other known peptides/proteins involved in different amyloid diseases." (PMID 35337074, 2022). "Transthyretin amyloidosis (ATTR amyloidosis) is a rare, life-threatening disease caused by the accumulation of variant or wild-type (ATTRwt amyloidosis) transthyretin amyloid fibrils in the heart, peripheral nerves, and other tissues and organs." (PMID 35717381, 2022). "Mounting clinical and preclinical evidence indicated that tafamidis and diflunisal reduced the progression of early- and late-onset ATTRwt and Val30Met (ATTRV30M) amyloidoses and diseases associated with other TTR variants." (PMID 35784752, 2022). "This has been shown to greatly reduce TTR deposition in patients with polyneuropathy caused by hATTR amyloidosis." (PMID 35269876, 2022). "Trigger finger associated with CTS and LSS has been reported as an initial manifestation of familial amyloid polyneuropathy (FAP) in a patient with TTR (Ile107Val) variant amyloidosis." (PMID 36551982, 2022). "Julian Gillmore (Centre for Amyloidosis and Acute Phase Proteins, University College London, UK) presented recently published work exploring a gene editing approach in humans to treat TTR-related amyloidosis disease, due to gain-of-function variants." (PMID 35260866, 2022). "Meanwhile, it also highlighted the significance of characterizing these biochemical properties prior to precision medical treatment for ATTRv amyloidosis patients carrying different TTR mutations." (PMID 36311011, 2022). "Patients who suffer from the hereditary transtherthyretin-mediated amyloidosis (hATTR) present with a mutation in a TTR gene leading to the production of an abhorrent TTR which is more susceptible to misfolding." (PMID 35056851, 2022).
amyloidosis (continued). "Hereditary amyloidogenic transthyretin (ATTRv) amyloidosis is a rare autosomal dominantly inherited disorder caused by mutations in the transthyretin (TTR) gene." (PMID 33188616, 2022). "Human TTR can cause two types of diseases due to misfolding, both of which belong to the amyloidosis family of diseases." (PMID 36364032, 2022). "The approved drug, Patisiran, to treat polyneuropathy associated with hereditary transthyretin-mediated amyloidosis, delivers the RNAi to the liver via lipid nanoparticles." (PMID 35620420, 2022). "TTR aggregation causes amyloidosis, which is associated with two different pathological conditions, i.e., hereditary familial amyloidosis (fATTR) and acquired senile systemic amyloidosis (sATTR)." (PMID 36614141, 2022). "Late-onset ATTRv-V30M amyloidosis and ATTRv caused by other TTR mutations often display a more severe course, with a median survival of about 7 years." (PMID 35386059, 2022). "Hereditary amyloidogenic transthyretin (ATTRv) amyloidosis is a rare, autosomal dominant, adult-onset systemic disease caused by a point mutation in the gene encodes transthyretin (TTR)." (PMID 35810210, 2022). "Cardiac accumulation of transthyretin deposits in the affected patients seen in amyloidosis due to transthyretin deposition (ATTR) cause clinical manifestations of HF." (PMID 35386116, 2022). "The in vitro oligomerisation occurs in both ATTRv and ATTRwt amyloidosis; this process is faster in ATTRv amyloidosis, where the stability of TTR is compromised by genetic mutations." (PMID 36009453, 2022). "LT removes the main source of the circulating mutated TTR (over 90%), reduces the rate of axonal degeneration, and was the first available treatment of V30M ATTRv amyloidosis." (PMID 35887731, 2022). "Hereditary transthyretin amyloidosis is an uncommon multisystem disorder caused by mutation of the transthyretin protein, leading to peripheral neuropathy often with autonomic features, cardiomyopathy, or a mixed phenotype." (PMID 35751086, 2022). "Hereditary transthyretin amyloidosis (ATTR amyloidosis) is a rare condition where a mutation in the transthyretin gene leads to systemic deposition of amyloid." (PMID 34991732, 2022). "Other types of amyloidoses with cardiac involvement include hereditary amyloidosis resulting from mutations in several genes, i.e., transthyretin and fibrinogen, and senile systemic amyloidosis." (PMID 35386116, 2022). "In the last years, TTR has gained considerable importance in the setting of amyloidosis, a protein misfolding disorder caused by the extracellular deposition of a β-sheet-rich protein as insoluble fibrils." (PMID 36009453, 2022). "Hereditary transthyretin amyloidosis is an autosomal dominant form of amyloidosis caused by an abnormality in transthyretin, with various ocular manifestations." (PMID 36156600, 2022). "hATTR amyloidosis is a genetic disorder that causes the buildup of abnormal TTR, which generally causes polyneuropathy when the build-up occurs in the peripheral nervous system." (PMID 35269876, 2022). "Cardiac events are the most frequent cause of morbidity and mortality in amyloidosis by immunoglobulin light and heavy chain, apo-serum amyloid A, TTR and apo-lipopro-tein A I." (PMID 36614141, 2022). "Beside primary RCM, it can manifest as a part of systemic diseases such as amyloidosis, which can also be genetically caused, for example, by mutations in the TTR (transthyretin) gene." (PMID 35456187, 2022). "We also provide a brief overview of the pathophysiologic, diagnostic, and therapeutic nuances of AL-, TTR-, wild type-, and β-2-microglobulin- associated (β2M) amyloidosis." (PMID 36341129, 2022). "The control cohort included 48 patients with wild‐type or mutated transthyretin amyloidosis (n = 34), AA amyloidosis (n = 1), or hypertrophic cardiomyopathy unrelated to an amyloidosis process (n = 13)." (PMID 36051065, 2022).